HERC2P4 (HERC2 pseudogene 4)
Synonyms: D16F37S5
Gene: Transcribed unprocessed pseudogene on chromosome 16 (32,152,111 to 32,187,070, reverse strand). Ensembl gene ENSG00000230267.
Diseases named in the same sentence as HERC2P4 in open-access papers:
HERC2P4 is named in the same sentence as 3 diseases in open-access papers, as found by Europe PMC text mining. Sharing a sentence is not in itself a finding about the gene and the disease. The quoted sentences say what the papers report.
lymph node metastasis (1 paper, 2020). "In addition, patients with lymph node metastasis had significantly higher expressions of PGM5P2, HERC2P4 and RRN3P2 but lower expressions of HLA-H and RPL13AP20 than those without lymph node metastasis." (PMID 33378744, 2020).
HERC2P4 also shares sentences with these, for which no sentence is quoted: breast carcinoma (1 paper); tumor (1).